YY1 (YY1 transcription factor)
Diseases named in the same sentence as YY1 in open-access papers (continued):
Sharing a sentence is not in itself a finding about the gene and the disease.
cervical carcinoma (continued). "The over-expression of YY1 and CDK6 proteins inversely correlated with miR-29 expression in CIN 1, 2 and cervical cancer, respectively." (PMID 25192291, 2014). "Moreover, it was demonstrated that YY1 and HPV E7 promote the expression of the lncRNA FANCI-2, thus contributing to cervical cancer development." (PMID 35408813, 2022). "YY1 can control human immunodeficiency virus (HIV) gene expression and viral titers, and deletion of YY1 binding sites in regulatory regions of human papilloma viruses correlates with increased viral gene expression and the development of cervical cancer." (PMID 24575094, 2014). "Studies have demonstrated that YY1 negatively regulates the HPV16 E6 expression in cervical cancer, suggesting that YY1 may target many downstream effectors to regulate the pathogenesis and progression of cervical cancer." (PMID 29470526, 2018).
osteosarcoma (25 papers, 2009 to 2024). A usually aggressive malignant bone-forming mesenchymal neoplasm, predominantly affecting adolescents and young adults. "In osteosarcoma, YY1 appears to be responsible for the tumor cells’ ability to invade and metastasize, and overexpression of YY1 in the primary site of osteosarcoma has shown to be associated with increased occurrence of metastasis and poor clinical outcome." (PMID 24674326, 2014). "Higher levels of oncogene YY1 expression in primary sites of osteosarcoma are associated with metastasis and poor clinical outcomes." (PMID 23311495, 2013). "Our study established that overexpression of YY1 in primary site of osteosarcoma is associated with the occurrence of metastasization and poor clinical prognosis." (PMID 22047406, 2011). "Overexpression of YY1 in primary site of osteosarcoma is associated with the occurrence of metastasis and poor clinical outcome." (PMID 22047406, 2011). "In conclusion, we demonstrated for the first time that high YY1 expression in osteosarcoma is associated with metastasis development and mortality independently of age, gender, histotype and presence of metastasis at baseline." (PMID 22047406, 2011). "The present study demonstrates that a high level of YY1 protein expression increases the risk of metastasis (4.69-fold) and poor survival (8.35-fold) in osteosarcoma patients independently of covariates such as age, gender, histotype, and chemonecrosis." (PMID 22047406, 2011). "Studies on osteosarcoma have shown that downregulation of YY1 negatively regulates the VEGF/CXCR4 axis pathway, thereby inhibiting angiogenesis and tumor cell migration by reducing the transcription and activity of MMPs." (PMID 38339244, 2024). "YY1 presents lower expression levels in pediatric osteosarcomas compared to normal human osteoblasts." (PMID 37081988, 2023). "The reduction of YY1 in osteosarcoma cells can interfere with their metastatic implantation and angiogenesis." (PMID 33235311, 2020). "An overexpression of YY1 was related to exhibit a strong correlation in patients with osteosarcoma, an aggressive bone tumor that occurs when a teenager matures into an adult, and it does this by silencing target genes." (PMID 25053986, 2014). "In contrast, a reduced expression of YY1 has been reported in melanomas, urothelial carcinomas and osteosarcomas." (PMID 25053986, 2014). "We report that the highest range of YY1 expression is a statistically significant prognostic factor setting the 5-year survival rate to 34% in patients with osteosarcoma." (PMID 22047406, 2011). "The design of the present study stemmed from our previous in vitro observations demonstrating that YY1 was overexpressed in osteosarcoma cells and tissues with more aggressive phenotype." (PMID 22047406, 2011). "We performed a prospective immunohistochemistry analysis to correlate YY1 immunostaining with metastatic development and survival in a selected homogeneous group of patients with osteosarcoma." (PMID 22047406, 2011). "YY1 is overexpressed in osteosarcoma cells and bioptic specimens, and is correlated with a high degree of malignancy." (PMID 22047406, 2011). "Additionally, a specific signal named Yin Yang 1 (YY1) protein from osteosarcoma (SaOS) cells plays a crucial role in driving the proliferation of human aortic endothelial cells (HAECs)." (PMID 38399305, 2024). "In osteosarcoma, the YY1 transcription factor induces upregulation of circFIRRE and partially increases mRNA and protein levels of LUZP1 by adsorbing miR-486-3p and miR-1225-5p, promoting tumor cell growth and angiogenesis, thereby driving primary osteosarcoma progression and lung metastasis." (PMID 37819576, 2023). "In osteosarcoma, the intrinsically highly expressed YY1 can bind to CBP, which in turn binds to c-Myc to downregulate YY1 acetylation and jointly decrease the transcriptional activity of the promoter of the integrin α3 subunit, thus promoting the malignant phenotype of osteosarcoma cells." (PMID 33985581, 2021).
osteosarcoma (continued). "Moreover, YY1 silencing has been shown to be sufficient to significantly reduce osteosarcoma metastatic growth and neoangiogenesis in a nude mice model." (PMID 22047406, 2011). "We studied the role of YY1 in osteosarcoma carcinogenesis and tumor progression." (PMID 22047406, 2011). "Moreover, in an in vivo mice model of osteosarcoma YY1 was also shown to play a key role in metastatic growth by regulating vascular supply." (PMID 22047406, 2011). "In addition, studies have shown that the expression of YY1 was upregulated in the malignancy of osteosarcoma, and silencing the expression of YY1 can significantly downregulate the activation of the VEGF/CXCR4 axis, thereby inhibiting the angiogenesis, invasion and metastasis." (PMID 37081988, 2023). "Thus, we designed a prospective study to analyze whether YY1 expression in the primary tumor of osteosarcoma patients could predict metastasis-free and overall survival." (PMID 22047406, 2011). "In this setting, YY1 is the first osteosarcoma marker whose overexpression has been correlated with low metastasis-free and poor overall survival in a higher frequency of cases (61% in the present study) than reported in other studies leading us to set a higher cut-off value (YY1 > 50%)." (PMID 22047406, 2011). "In fact, although Cxcr4 is required for osteoblastic differentiation, it also seems to intervene, together with YY1 and VEGF, in the pathogenesis of the malignant phenotype of osteosarcoma by promoting cell invasiveness and metastasis." (PMID 34638956, 2021). "To date, there is no clinical evidence of YY1 involvement in outcome of patients with osteosarcoma." (PMID 22047406, 2011). "The fact that YY1 expression can render a cell resistant to apoptosis may explain why levels of YY1 are increased in certain types of cancer such as osteosarcoma, non-melanoma skin cancer, and acute myeloid leukemia." (PMID 19566924, 2009).
ovarian carcinoma (25 papers, 2010 to 2025). A malignant neoplasm originating from the surface ovarian epithelium. "YY1 also stimulates the FASN-HIF1α pathway, causing ferroptosis suppression and the growth of ovarian cancer by inducing USP43." (PMID 41009346, 2025). "In ovarian cancer, YY1 induces the transcription of PART1, enhances resistance to cisplatin, and inhibits apoptosis by modulating the miR-512-3p/chromatin accessibility complex subunit 1 (CHRAC1) axis." (PMID 40867514, 2025). "In ovarian cancer, YY1 expression is upregulated by CD24, a surface marker associated with CSC phenotypes and malignant progression." (PMID 40867514, 2025). "This study demonstrated that CD24 induced the expression of miR-130a and 301a via Src or FAK-mediated STAT4 and YY1 phosphorylation in ovarian cancer cells, which led to cellular quiescence-like state and chemoresistance." (PMID 38360723, 2024). "We explored the potential of YY1, FDX1, DLD, DLAT, and PDHB to serve as non-invasive diagnostic markers of ovarian cancer." (PMID 36484005, 2022). "This allowed us to analyze in detail the potential of anisomycin in inducing cuproptosis in ovarian cancer stem cells by activating the specific transcription factor YY1 and transactivating important genes related to the lipoic acid pathway." (PMID 36484005, 2022). "The Kaplan-Meier plotter analysis revealed that YY1 was also significantly negatively correlated with the life cycle of ovarian cancer patients." (PMID 36484005, 2022). "Further analysis showed that the transcription copy number of the YY1 gene in ovarian cancer patients was significantly elevated relative to that in the control group." (PMID 36484005, 2022). "We therefore reanalyzed the cDNA microarray analysis data from the ovarian cancer stem cells treated with anisomycin and confirmed that the expression levels of YY1 were significantly reduced in the anisomycin-treated group." (PMID 36484005, 2022). "Bioinformatics analysis revealed that four core factors (lipoic acid pathway FDX1, DLD, DLAT, PDH), and transcription factor YY1 were highly expressed in ovarian cancer tissues and were significantly correlated with an unfavorable prognosis." (PMID 36484005, 2022). "Multiple gene-comparison analysis showed that the expression levels of YY1 were also significantly different between the tumor tissues of ovarian cancer patients and the control group (T vs N: 1.32; p<0.05)." (PMID 36484005, 2022). "We used an exosome database for screening and found that the levels of FDX1, DLD, DLAT, PDHB, and YY1 in peripheral blood exosomes from ovarian cancer patients were significantly higher than those in the normal controls." (PMID 36484005, 2022). "miR-381 inhibits epithelial ovarian cancer cell proliferation, migration and invasion, via suppression of its target gene, YY1." (PMID 28977942, 2017). "Because YY1 suppression inhibits cancer cell migration and that the migration is strongly associated with microtubule dynamics, YY1 may have a role in the transcription of proteins that are involved in microtubule dynamics and, hence, also in metastasis of the ovarian cancer cells." (PMID 25053986, 2014). "YY1 overexpression in ovarian cancer, in contrast to most cancers, correlated with higher ovarian cancer survival rates." (PMID 25053986, 2014). "Because the array was manufactured, several new correlations of gene expression with drugs active in ovarian cancer have since been described, for example gemcitabine in which ribonucleotide reductase subunits may be involved, and paclitaxel in which YY1 expression has been implicated." (PMID 20700122, 2010). "YY1 inhibits SHLD1 transcription, thereby leading cross-resistance to poly ADP-ribose polymerase (PARP) inhibitor and cisplatin in breast cancer susceptibility gene 1 (BRCA1)-deficient ovarian cancer cells." (PMID 40867514, 2025).
ovarian carcinoma (continued). "In conclusion, our study indicates that the detection of FDX1, DLAT, YY1 levels in the peripheral blood exosomes of patients with ovarian cancer can be used to quickly, accurately, and effectively predict the progress and prognosis of patients with ovarian cancer." (PMID 36484005, 2022). "We therefore hypothesize that the direct target of anisomycin-induced cuproptosis in ovarian cancer stem cells is transcription factor YY1." (PMID 36484005, 2022). "In addition, the expression levels of YY1 in the tissue samples from ovarian cancer patients were significantly positively correlated with the expression levels of FDX1, DLD, DLAT, PDHB, and other genes." (PMID 36484005, 2022). "Therefore, our molecular biology experiments combined with bioinformatics analysis results suggest that the direct target of anisomycin-induced cuproptosis in ovarian cancer stem cells is probably a YY1 transcription factor." (PMID 36484005, 2022). "This suggests that YY1 may affect the prognosis of ovarian cancer patients through USP43." (PMID 40890129, 2025). "Moreover, YY1 cooperates with transcription factor 3 (E2F3) proteins to enhance the expression of microtubule-related genes, promote the ovarian cancer cell mesenchymal transition, and increase the resistance to paclitaxel and docetaxel." (PMID 40867514, 2025). "In addition, there is a negative correlation between YY1 level with survival of ovarian cancer patients." (PMID 39910959, 2025).
liver cancer (21 papers, 2014 to 2025). An epithelial or non-epithelial malignant neoplasm that arises from the liver. "In this study, we identified the transcription factor YY1, linked to resistance to PD‐1 therapy in HCC, and demonstrated its role in fostering drug resistance by upregulating PD‐L1 expression in liver cancer cells." (PMID 41322030, 2025). "Yin-Yang 1 (YY1), a transcription factor linked to cancer progression, exhibits a positive correlation with QKI expression in liver cancer." (PMID 40290118, 2025). "Conversely, upregulated miR-34a-5p suppresses the invasion and metastasis of liver cancer by targeting the transcription factor YY1 to mediate MYCT1 upregulation." (PMID 38256049, 2024). "Other studies have shown that 3-HAA can induce apoptosis in liver cancer cells as a ligand-activated transcription factor YY1 and has anti-cancer effects." (PMID 37908541, 2023). "To investigate the role of YY1 in regulating hepatic gene expression, we knocked down YY1 expression in the liver cancer cell line HepG2 employing both lentiviral-mediated shRNA and artificial miRNA (amiRNA)." (PMID 34099540, 2021). "Moreover, YY1 acts as a pivotal regulator in oxymatrine-induced liver cancer ferroptosis by modulating the silent information regulator 1 (SIRT1)/YY1/GPX4 signaling axis." (PMID 40867514, 2025). "Moreover, USP7 and YY1 expression levels were positively correlated with the clinical stage of liver cancer in TCGA." (PMID 37408047, 2023). "Clinical data were analyzed to determine the effect of USP7 and YY1 on liver cancer." (PMID 37408047, 2023). "Furthermore, YY1 mRNA levels and its upregulated targets in conditions of eIF6 depletion individually showed a consistent trend with benign prognosis in primary liver cancer." (PMID 34385447, 2021). "Remarkably, a similar enrichment for YY1, NRF1, E2F4, and FOXP3 TFs was also identified by GO-Elite in both the livers of miR-122 KO animals (GSE31453) and in the mouse model for liver cancer (GSE27713)." (PMID 37627157, 2023). "Eight modules are both CNV-TF regulated and CNV-gene enriched, and among these eight CNV-TFs, YY1, MZF1, DAND5, NFYB, ESR1 have been reported in liver cancer development and metastasis." (PMID 24897108, 2014). "Specifically, YY1, functioning as a transcription factor, directly amplifies the expression of GALNT16, a glycosyltransferase, thereby enhancing PD‐L1 glycosylation in liver cancer cells and curbing PD‐L1 degradation via the ubiquitination pathway." (PMID 41322030, 2025). "We found that NEO1 was positively regulated by HDAC1, 2, and YY1, whereas was negatively regulated by HDAC6 in LIHC, suggesting that NEO1 may play an important role in the proliferation and apoptosis of liver cancer cells." (PMID 41407823, 2025). "In research on thioacetamide mouse liver cancer model, CpG island hypermethylation of WDR45B and Yin Yang 1 (YY1) was observed in the pretumor liver disease foci of mice, which was involved in the regulation of cell cycle and apoptosis, promoting tumor formation." (PMID 36900050, 2023). "In conclusion, hyperoside exerts its anti-liver cancer effect by inhibiting the proliferation of liver cancer cells, arresting their cell cycle and effectively inhibiting the activity of the YY1 complex, the expression of QKI and the invasion and metastasis of liver cancer cells." (PMID 35566359, 2022). "Furthermore, YY1 can also suppress fatty acid oxidation by targeting PGC‐1β and thus lead to lipid accumulation in liver cancer cells." (PMID 33118286, 2020).
cholangiocarcinoma (20 papers, 2020 to 2025). A carcinoma that arises from the intrahepatic biliary tree (intrahepatic cholangiocarcinoma) or from the junction, or adjacent to the junction, of the right and left hepatic ducts (hilar cholangiocarcinoma). "Circ-CCAC1 (Cholangiocarcinoma-associated circular RNA 1) facilitated CCA growth and migration via sponging miR-514a-5p to elevate the expression of YY1 (Yin Yang 1) and CAMLG (calcium modulating ligand)." (PMID 35255950, 2022). "In vivo studies have demonstrated that the upregulation of Yin-Yang 1 (YY1) expression by the sponging of miR-514a-5p promoted progression and accelerated the tumorigenesis and metastasis of cholangiocarcinoma (CCA)." (PMID 37753074, 2023). "YY1 was also found to be up-regulated in cholangiocarcinoma tissues compared with normal tissues, and high YY1 expression predicted poor prognosis." (PMID 39524541, 2023). "Among the predicted transcription factors, YY1 has been rarely reported in cholangiocarcinoma, and was verified using the luciferase reporter gene assay." (PMID 34933678, 2021). "YY1, a transcription factor, is overexpressed in a diverse range of tumors, including cholangiocarcinoma." (PMID 34898474, 2021). "Increases cell progression by sponging miR-514a-5p to upregulate YY1, and induces angiogenesis in cholangiocarcinoma." (PMID 33363174, 2020). "However, another study showed that the knockdown of YY1 in cholangiocarcinoma cell lines CCLP1 and RBE resulted in a decrease in PCIF1 expression at both the translational and transcriptional levels." (PMID 39524541, 2023). "A previous study demonstrated that circ-CCAC1 elevated YY1 expression to promote cholangiocarcinoma (CCA) by sponging miR-514a-5p in CCA cells while elevating SH3GL2 expression to enhance cell permeability by directly sequestering EZH2 in the cytoplasm of human umbilical vein endothelial cells." (PMID 35045883, 2022). "Also, YY1 had been shown to be involved in various tumors progression and associated with adverse clinical prognosis in tumor patients, for instance, YY1 stimulated LINC00667 transcription that enhanced the proliferation of cholangiocarcinoma." (PMID 34898474, 2021). "In particular, in cholangiocarcinoma (CCA), circ-CCAC1 promotes CCA progression and angiogenesis by degradation (sponging) miR-514a-5p, a negative regulator of YY1." (PMID 38339244, 2024). "For example, exosomal cholangiocarcinoma (CCA)-associated circular RNA 1 (circ-CCAC1) derived from ERBB2 gene was discovered to sponge miR-514a-5p to upregulate Yin Yang 1 (YY1), inducing CCA angiogenesis, and regulate CCA tumorigenesis and metastasis." (PMID 38177102, 2024). "A recent study showed that circCCAC1 promotes cholangiocarcinoma (CCA) tumorigenesis by sponging miR-514a-5p that targets YY1." (PMID 33317550, 2020). "The chromatin immunoprecipitation–sequencing results suggested that in cholangiocarcinoma, six genes including PCIF1 were likely to be transcriptionally regulated by YY1." (PMID 39524541, 2023). "In cholangiocarcinoma (CCA) cells, circ-CCAC1 upregulated the Yin Yang 1 (YY1) expression by sponging miR-514a-5p, thereby promoting the malignant progression of tumor cells." (PMID 37046819, 2023). "It is important to note that all cholangiocarcinoma, DLBC, and KIRP cases with genetic alteration had copy number deletion of YY1." (PMID 35791393, 2022). "Moreover, YY1 could increase vascular endothelial permeability in cholangiocarcinoma." (PMID 34267179, 2021). "Overall, YY1/eIF4A3/circ-ZNF609/miR-432-5p/LRRC1 have a significant role in progression of cholangiocarcinoma, and circ-ZNF609 is expected to become a novel biomarker for targeted therapy and prognosis evaluation of cholangiocarcinoma." (PMID 34898474, 2021).